MFN2 (mitofusin 2)
Diseases named in the same sentence as MFN2 in open-access papers (continued):
Sharing a sentence is not in itself a finding about the gene and the disease.
Insulin resistance (continued). "MicroRNA-106b induces mitochondrial dysfunction and insulin resistance in C2C12 myotubes by targeting mitofusin-2." (PMID 27635130, 2016). "Overexpression of miR-106b led to mitochondrial dysfunction and insulin resistance in C2C12 myotubes by targeting the expression of mitofusin-2 (Mfn2), as well as PGC-1α." (PMID 27215643, 2016). "Based on these data, we propose that the reduced Mfn2 expression upon exposure to the HL diet participates in the insulin resistance that affects the liver under these conditions." (PMID 24663492, 2014). "In the current study, our data demonstrate that overexpression of MFN2 significantly restored insulin sensitivity and reduced the levels of BG and plasma insulin in rats, suggesting MFN2 as a potential therapeutic target in insulin resistance." (PMID 23815800, 2013). "In conclusion, our data suggest that MFN2 ameliorates insulin resistance induced by a high-fat diet through upregulation of CPT1, which relieves lipid intermediates accumulation in skeletal muscle." (PMID 23815800, 2013). "MFN2 overexpression can rescue insulin resistance, possibly by upregulating CPT1 expression leading to reduction in the accumulation of lipid intermediates in skeletal muscle." (PMID 23815800, 2013). "It is speculated that exercise may alleviate insulin resistance by upregulating the expression of Mfn2, promoting the repair of MAMs structure to improve ER stress." (PMID 38542170, 2024). "Our study shows a significant reduction in Opa1 and Mfn2 expression in the skeletal muscle, and this could be responsible for the abnormal mitochondrial structure and could potentially contribute to insulin resistance." (PMID 35334815, 2022). "As a crucial tethering protein at MAMs, Mfn2 is actively involved in insulin resistance." (PMID 33339212, 2020). "On the contrary, the anti-inflammatory effect of omega-3 PUFA may contribute to induce Mfn2 expression, thereby counteracting insulin resistance." (PMID 31130874, 2019). "Moreover, ablation of MFN2 in adipocytes was beneficial, as it conferred better tolerance to glucose and protected against high-fat induced insulin resistance." (PMID 31156446, 2019). "Importantly, PGC‐1α or Mfn‐2 overexpression reversed the mitochondrial dysfunction induced by NEFAs and improved insulin resistance in hepatocytes." (PMID 29602237, 2018). "Our data demonstrated that Mfn‐2 overexpression could markedly decrease the lipotoxicity of NEFAs on mitochondrial function and insulin sensitivity, indicating that Mfn‐2 is a potential therapeutic target for insulin resistance in NASH." (PMID 29602237, 2018). "However, Mfn2 activity in BAT contributes to insulin resistance, as Mfn2 excision in brown adipocytes, using Ucp1 promoter‐driven Cre, improves insulin sensitivity in obese mice." (PMID 28539390, 2017). "On the other hand, Mfn2 deficiency was shown to be associated with active JNK, endoplasmic reticulum stress, enhanced hydrogen peroxide concentration, altered ROS handling, and susceptibility to insulin resistance in liver and muscle." (PMID 24987494, 2014). "In addition, expression of MFN2 improved HFD-induced insulin resistance and glucose homeostasis in liver." (PMID 24658162, 2014). "Furthermore, an MFN2-expressing adenovirus was used to investigate the mechanism by which MFN2 relieves skeletal muscle lipid intermediate accumulation and ameliorates insulin resistance." (PMID 23815800, 2013). "Thus, it can be speculated that the pro-inflammatory effects of long-chain saturated fatty acids may be responsible for the reduction in Mfn2, which in turn may contribute to the development of insulin resistance." (PMID 31130874, 2019). "In addition, given that Mfn2 play an important role in both ER-mitochondria connection and in insulin resistance prevention, the link between Mfn2 and Ca2+ flux in mitochondria should be further investigate in omega 3 PUFA beneficial effect involving inflammasome inactivation." (PMID 29538286, 2018).
Insulin resistance (continued). "Diabetic cardiomyopathy is marked by reduced expression of fusion proteins (Mfn1, Mfn2, OPA1), increased fission, and overproduction of reactive oxygen species (ROS), which contribute to insulin resistance and cardiac dysfunction." (PMID 41000071, 2025). "Furthermore, just as in the POMC-neuron-specific Mfn2 knockout mouse model, mice with an adipocyte (adiponectin)-specifc Mfn2 deletion induced in adulthood gained body weight accompanied by increased plasma leptin and glucose levels, as well as by insulin resistance." (PMID 34114603, 2021). "Prevention of ER stress in Mfn2 KO livers decreased NASH and insulin resistance and reversed the decrease in fat oxidation induced by Mfn2 deletion." (PMID 33276146, 2021). "In agreement, the overexpression of Mfn2 partially restored the MAM contact area and ameliorated the palmitic acid-induced insulin resistance, improving Ser473 phosphorylation of Akt." (PMID 29538286, 2018). "Whichever the response to Mfn2 deletion, it provides a superior capacity to prevent HFD‐induced insulin resistance." (PMID 28539390, 2017). "Protection from insulin resistance is parallel with gender‐specific changes in BAT function, which promote an enhancement of nutrient utilization capacity supplying ATP in Mfn2‐deleted BAT." (PMID 28539390, 2017). "We report that the mitochondrial fusion protein Mitofusin 2 (Mfn2) in BAT is essential for cold‐stimulated thermogenesis, but promotes insulin resistance in obese mice." (PMID 28539390, 2017). "Furthermore, overexpression of Mfn2 partially restored MAM contact sites and improved palmitic acid-induced insulin resistance, enhancing Akt Ser473 phosphorylation." (PMID 39966707, 2025). "One striking exception to this is the recent discovery that a point mutation in human mitofusin 2 (MFN2) produces profound adipose tissue dysfunction, non-alcoholic fatty liver disease, insulin resistance and type 2 diabetes." (PMID 39739772, 2024). "At the same time, lower mitochondrial ROS level, higher mitochondrial membrane potential, and attenuated insulin resistance were observed in HFD rats following exercise intervention, which confirmed the role of Mfn2 in exercise-induced improvement in insulin sensitivity." (PMID 33339212, 2020).
neuropathy (40 papers, 2014 to 2026). A disorder affecting the nervous system that manifests with pain, tingling, numbness, and/or muscle weakness. "l-arginine has shown promise in treating mitochondrial disorders, though its effect on MFN2-associated neuropathy remains uncertain." (PMID 41932155, 2026). "Many causal mutations are nonsense, frameshift or essential splice site mutations, indicating that neuropathy is caused by MFN2 haploinsufficiency." (PMID 40759924, 2025). "Heterozygous mutations in the MFN2 gene (mitofusin 2) are associated with the axonal CMT2A neuropathy, which accounts for 20–30% of all axonal CMTs." (PMID 38678519, 2024). "Mfn2 knock-out mice die in early embryogenesis while mice homozygous for either of two human neuropathy-associated, GTPase null missense mutations (H361Y or R94W) die on day 0–1." (PMID 36722855, 2023). "We generated a Mfn2K357T-expressing KI mouse model of CMT2A based on a novel MFN2 mutation discovered in a CMT2A patient with early-onset severe neuropathy." (PMID 34769001, 2021). "His father carrying a heterozygous variant in MFN2 (c.839G>A, p.R280H) had subclinical neuropathy with diminished tendon reflexes in the upper and lower limbs as the only clinical sign." (PMID 35153971, 2021). "A 4-year-old boy was evaluated in our clinic with a severe, early-onset (by 2 years of age) neuropathy associated with a de novo, novel, missense mutation in exon 11 (RefSeq accession number: NM_014874.4) of the MFN2 gene (located on chromosome 1 (Chr." (PMID 34769001, 2021). "Patients with neuropathy, optic atrophy and other CNS disorders have been identified with Mfn2 mutations." (PMID 32455165, 2020). "On the other hand, arguing against the notion of muscle loss downstream of neuropathy, mitochondrial myopathy is seen in a skeletal muscle–specific MFN2 loss-of-function study in animal models, highlighting the importance of the protein in tissues such as skeletal muscle." (PMID 40175090, 2025). "Such neuropathy is commonly observed in people with heterozygous loss of MFN2 function." (PMID 36722855, 2023). "While only a limited number of CMT2A MFN2 variants have been investigated for their role in MERCs,26,38 disruption of contacts between mitochondria and ER seems to be a common theme underlying neuropathies." (PMID 38274408, 2021). "As well as considering pharmacological approaches, future screens may also seek genetic modifiers of the phenotype, including knockdown of the Mfn2 paralogue Mfn1, which has been shown in some contexts to compensate for at least some neuropathy-causing mitofusin 2 mutations." (PMID 40759924, 2025). "Moreover, although there are other mutations which can cause CMT type 2, mutations in Mitofusin 2 have been known to cause a severe neuropathy compared to others, with the pattern of the condition being predominantly motor or motor deformity combined with proprioception loss." (PMID 31245205, 2019). "This electrophysiological heterogeneity reflects the broad phenotypic spectrum of MFN2‐related neuropathy and the importance of thorough nerve conduction studies." (PMID 41030121, 2026). "Advances in molecular genetics have identified key causative genes, including PMP22, MPZ, MFN2, TTR, EGR2, and CX32 (GJB1), which are implicated in Charcot–Marie–Tooth disease, Dejerine–Sottas syndrome, and related neuropathies." (PMID 41595476, 2026). "Beyond supporting diagnosis of CMT2A and of CMT-related neuropathies, this work improves our knowledge of MFN2 function and of its link to CMT2A." (PMID 40121276, 2025). "In case 7, the comprehensive phenotyping allowed to identify a full-blown CANVAS syndrome on top of a MFN2 neuropathy." (PMID 39544699, 2024). "We have proposed that mitochondrial motility defects induced by mutant MFN2 are responsible for clinical neuropathies because neurons have long axonal and dendritic processes that make them critically dependent upon mitochondrial transport." (PMID 37910431, 2023).
neuropathy (continued). "Vocal cord paralysis has been reported as an early, severe, and frequent symptom of GDAP1-associated neuropathy [CMT4A], often followed by diaphragmatic dysfunction, and in both AD and AR inheritance forms of CMT2A (mutations in the MFN2 gene)." (PMID 37966693, 2023). "Knockin (KI) mice engineered to carry Mfn2 Q400 develop a perinatal cardiomyopathy, whereas Mfn2 T105M KI mice develop a CMT2A-like neuropathy and Mfn2 M376V KI mice appear phenotypically normal." (PMID 37910431, 2023). "According to larger studies following comparable protocols, we can genetically identify the four most frequent genes (PMP22, GJB1/Cx32, MPZ/P0, MFN2) in 40–60% of patients in whom an inherited neuropathy is suspected." (PMID 34438578, 2021). "Our cohort had few cases of MFN2 neuropathy (3%), like other Spanish series, yet this contrasted with other pediatric cohorts from the INC5 and in France, in which MFN2 mutations were the second most frequent." (PMID 34323022, 2021). "Mitofusin-2 (MFN2) neuropathy must be cited in addition to these “conventional” mitochondrial disorders." (PMID 33802970, 2021). "There is one described report of an MFN2 patient having neuropathy with sensory ataxia and optic atrophy." (PMID 38274408, 2021). "MFN2-related disease is highly variable in its severity, ranging from severe, early-onset neuropathy to very late-onset presentations with low levels of disability." (PMID 33810506, 2021). "Very rarely, MFN2 homozygous mutations have been reported in patients with multiple lipomatosis and neuropathy, linking MFN2 with lipid metabolism possibly thorough its role in MAMs organization." (PMID 33806088, 2021). "Studies indicate that, in cells with lower expression of Mfn1, or when higher levels of mitochondrial fusion is required, such as in peripheral neurons, mutations in Mfn2 lead to axonal degeneration, characteristic in CMT2A neuropathy." (PMID 32455165, 2020). "Rodent CMT models have advanced understanding of neuropathy; however, regarding MFN2 of CMT2A, which is the most frequent subtype of axonal CMT, it used to be difficult to reproduce the phenotype in rodent due to embryonic lethality." (PMID 33049996, 2020). "In the context of the neuropathy Charcot-Marie-Tooth Type 2A (CMT2A), which is caused by dominant-negative mutations in MFN2, it was suggested that MFN2 behaves as an inhibitor of mitophagy." (PMID 31156446, 2019). "In 2015, a homozygous missense mutation, p.Arg707Trp, was identified in MFN2, or mitofusin 2, in three patients with MSL and neuropathy from two families." (PMID 28414270, 2017). "Notably, two patients exhibited digenic inheritance involving MFN2 and either PMP22 or SOD1, highlighting the genetic complexity underlying inherited neuropathies." (PMID 41030121, 2026). "Not all patients with MFN2-related lipodystrophy have peripheral neuropathy, suggesting that penetrance and/or expressivity of MFN2 R707W-related neuropathy may be lower than that of lipodystrophy." (PMID 40759924, 2025). "Lack of conformational malleability did not distinguish between the cardiomyopathy- vs. the neuropathy-associated MFN2 mutants." (PMID 37910431, 2023). "Although pathogenic variants in MFN2 are one of the major genetic causes of neuropathy, it is somewhat surprising that none have been described in MFN1." (PMID 33810506, 2021). "Of interest, the frameshift p.V205Sfs*26 variant in MFN2 associated with subclinical neuropathy in our study suggested that MFN2 is not sensitive to haploinsufficiency." (PMID 35153971, 2021). "All cases of MFN2-related MSL have featured biallelic mutations including at least one MFN2 p.Arg707Trp allele, and many, but not all, patients have shown early-onset neuropathy in addition." (PMID 28414270, 2017).
neuropathy (continued). "Since MFN2 gene has been recognized to be a major cause of CMT2A, more than 100 disease-associated mutations and many variants of unknown significance of MFN2 have been identified, which broaden the phenotypic spectrum of MFN2-related neuropathy." (PMID 34721278, 2021). "In addition, a link of MFN2 to the most common neuropathies has also been suggested." (PMID 31156446, 2019). "CMT2A is a dominant neuropathy in which patients are heterozygous for MFN2 mutations, but it is not known whether the CMT2A phenotype results from MFN2 haploinsufficiency is a dominant negative effect on the WT allele or is semi-dominant." (PMID 30649465, 2019). "The patient presentation, with late-onset myopathy, but without neuropathy, offers a unique opportunity to separate the pathological outcomes of MFN2 dysfunction by examining the specific mechanism leading to myopathy." (PMID 40175090, 2025). "While certain forms of mitochondrial CMT, such as MFN2, SANDO, and MNGIE, are well documented, and have been detected by candidate gene sequencing in the past, the mechanism leading to a predominant neuropathy in some individuals remains unclear." (PMID 38549004, 2024).
Charcot-Marie-Tooth disease type 2A (37 papers, 2006 to 2025). "This study examined the effects of MFN2 catalytic activity and allostery on defective mitochondrial fusion and neural transport in relation to Charcot-Marie-Tooth disease type 2A, an incurable peripheral neuropathy brought on by MFN2 mutations." (PMID 39896143, 2025). "Pathogenic variants in the nuclear gene MFN2 lead to Charcot-Marie-Tooth disease type 2A and encode for the protein mitofusin 2, a mitochondrial outer membrane protein involved in mitochondrial fusion." (PMID 41149856, 2025). "The idea of SARM1 contributing to chronic neurodegeneration by a feed-forward mechanism centered on mitochondrial pathology has been recently proposed in Charcot-Marie-Tooth disease type 2A caused by mutations in the mitochondrial gene mitofusin 2 (MFN2)." (PMID 37503611, 2023). "Charcot-Marie-Tooth disease type 2A is associated with around 100 different dominant mitofusin 2 mutations, with varying degrees of severity." (PMID 36556475, 2022). "Mutations in MFN2 are associated with peripheral nerve degeneration in Charcot-Marie-Tooth disease type 2A, while Willin/FRMD6 is involved in peripheral nerve repair." (PMID 36231104, 2022). "Charcot-Marie-Tooth disease type 2A (CMT2A) is the most common hereditary axonal neuropathy caused by mutations in MFN2 encoding Mitofusin-2, a multifunctional protein located in the outer mitochondrial membrane." (PMID 34769001, 2021). "Mutations in Mfn2 have been linked to Charcot-Marie-tooth disease type 2A (CMT2A), which involves slow and progressive degeneration of peripheral neurons, mostly affecting the extremities." (PMID 32714603, 2020). "Mutations in MFN2 are associated with Charcot-Marie-Tooth disease type 2A (CMT2A), accounting for 4–7% of all genetically diagnosed CMT and 30–40% of genetically diagnosed axonal CMT (CMT2)." (PMID 33415332, 2020). "Charcot-Marie-Tooth disease type 2A (CMT2A) is an autosomal dominant neuropathy caused by mutations in the mitofusin 2 gene (MFN2)." (PMID 30442897, 2018). "Mfn2 mutations have been identified in patients with Charcot-Marie-Tooth Disease Type 2A (CMT2A), a neuromuscular disorder that impacts motor nerve conduction." (PMID 28513539, 2017). "Charcot-Marie-Tooth disease type 2A is caused by mutations in the MFN2 (mitofusin 2) gene (OMIM 608507)." (PMID 28063088, 2017). "Charcot-Marie-Tooth disease type 2A (CMT2A) is an autosomal dominant axonal peripheral neuropathy caused by mutations in the mitofusin 2 gene (MFN2)." (PMID 28076385, 2017). "Charcot-Marie-Tooth disease type 2A has been linked with an Mfn2 mutation that results in the loss of Mfn2 activity." (PMID 28074080, 2016). "Mutations in the MFN2 gene have been reported as the primary cause of Charcot-Marie-Tooth disease type 2A." (PMID 16762064, 2006). "SARM1 has been shown to play a prodegenerative role in axonopathies characterized by mitochondrial dysfunction, such as CMT (Charcot-Marie-Tooth) disease type 2A caused by mutations in the MFN2 (mitofusin 2) gene (Loreto and others 2020; Sato-Yamada and others 2022)." (PMID 37002660, 2024). "Interestingly, one patient with co-occurrence of ALS and Charcot-Marie-Tooth disease type 2A associated with a novel mutation in the MFN2 gene has been also described, but this co-occurrence was supposed to be casual rather than causal." (PMID 37547466, 2023). "Interestingly, similar membranous structures were observed in neurons from Drosophila with a Charcot-Marie-Tooth disease type 2A (CMT2A) MFN2 mutation (R364Wlike) that results in mitochondrial hyperfusion." (PMID 33762963, 2021). "In addition, mutations in MFN2 have been found in axonal Charcot-Marie-Tooth disease type 2A and mice with the mutation R95Q in MFN2 developed this pathology." (PMID 33782711, 2021). "We tackled some of these issues in fibroblasts derived from a Charcot-Marie-Tooth disease type 2A (CMT2A) patient with a mutation in the GTPase domain of MFN2." (PMID 40396043, 2022).